KIT (KIT proto-oncogene, receptor tyrosine kinase)
Diseases named in the same sentence as KIT in open-access papers (continued):
Sharing a sentence is not in itself a finding about the gene and the disease.
thymoma (39 papers, 2013 to 2026). A neoplasm arising from the epithelial cells of the thymus. "The ERBB2 and KIT variants were detected in B2B3 thymomas, and the FOXL2 variant in a micronodular thymoma with lymphoid stroma." (PMID 35884448, 2022). "In another type B3 thymoma metastatic to the liver, a Y823D mutation in the KIT gene was identified." (PMID 35749302, 2022). "The results of the TCGA study of thymic epithelial tumors confirmed previous studies that revealed absence of targetable mutations as tissue-based biomarkers in thymomas and presence of only rare clinically meaningful mutations (e.g., of the KIT gene) in TCs." (PMID 33674910, 2021). "For instance, only two known cancer genes were found to be mutated in over 5% of thymomas (MUC16 and HRAS), testicular germ cell tumours (KRAS and KIT), and thyroid carcinomas (BRAF and NRAS)." (PMID 37550388, 2023). "In this study, 3 of 19 (16%) thymomas exhibited missense variants of uncertain clinical significance in ERBB2 [p.(Ser703Arg)], KIT [p.(Ile690Val)], and FOXL2 [p.(Pro157Ser)]." (PMID 35884448, 2022). "Briefly, KIT and CD5 are positive in ~ 80% of TSQCCs, whereas ~ 3% of thymomas show positivity for KIT or CD51,4." (PMID 32704057, 2020). "KIT and CD5 were positive in 17 (100%) and 16 (94.1%) TSQCCs, respectively, whereas one (0.9%) type B3 thymoma showed double positivity for KIT and CD5." (PMID 32704057, 2020). "KIT IHC and mutational analysis of the tumors noted positivity in only one of the thymoma samples, while the remainder were either negative or testing was not available." (PMID 38254905, 2024). "KIT immunohistochemical positivity can be seen in up to 73–86% of TC but only in 2% of thymomas." (PMID 37893096, 2023). "The KIT Y823D mutation we observed in a type B3 thymoma was previously not reported as being sensitive to KIT inhibitors." (PMID 35749302, 2022). "No pathogenic variants were found in thymomas, although a few variants of uncertain clinical significance were present in KIT, ERBB2, and FOXL2." (PMID 35884448, 2022). "On the other hand, c-KIT overexpression is rare in TMs (2–4%), and no known mutation, except for a KIT deletion in a patient with AB thymoma reported on TCGA PanCancer Atlas, have been reported." (PMID 33915954, 2021). "For example, an analysis of tissue microarrays found that CA9 serves as a diagnostic marker that distinguishes TCs from type B3 thymomas, though the diagnostic specificity and sensitivity of CA9 was not higher compared with those of glucose transporter 1 (GLUT-1) or KIT." (PMID 30863491, 2019). "In addition, PRAME-positive thymomas are always KIT- and CD5-negative." (PMID 32704057, 2020). "The expression of CD5, KIT (CD117), EMA (MUC1), and EZH2 is frequently observed in thymic SCCs (75–85%), but is rarely expressed in thymomas (usually <5%)." (PMID 34069513, 2021). "KIT and CD5 were positive in 17 (100%) and 16 (94.1%) TSQCCs, whereas one (0.9%) type B3 thymoma showed double positivity for KIT and CD5." (PMID 32704057, 2020). "A multicenter prospective cohort assessed the efficacy of sunitinib, VEGFRs, KIT, PDGFRs, and tyrosine kinase inhibitor (TKI) in twenty-eight patients (nineteen male/nine female) with stage III and IV thymomas and TC who already received other systemic treatments." (PMID 38069386, 2023). "KIT (also known as CD117) and CD5 are established diagnostic markers for TSQCC and are almost always negative in thymoma, with some exceptions." (PMID 32704057, 2020). "However, differential diagnosis for type B3 thymoma is sometimes challenging, even with established markers for TSQCC, including KIT and CD5, which are expressed in ~ 80% of TSQCCs and ~ 3% of thymomas." (PMID 32704057, 2020). "The KIT-/CD5-positive type B3 thymoma was negative for PRAME." (PMID 32704057, 2020).
thymoma (continued). "In these studies, c-KIT expression positively correlated with EMT markers N-cadherin, Twist, and Snail and negatively with E-cadherin, suggesting that the immunohistochemical analysis of those proteins could be important to distinguish between thymic cancer and thymoma." (PMID 35490363, 2022). "Moreover, an intriguing observation emerges among approximately 70% of thymic squamous cell carcinomas, wherein all KIT-positive cases exhibit a distinctive tuft cell–like phenotype characterized by the robust expression of POU2F3, an event absent in thymomas." (PMID 37849766, 2023). "No cases of type B3 thymoma showed simultaneous positivity for PRAME, KIT, and CD5." (PMID 32704057, 2020).
renal cell carcinoma (38 papers, 2007 to 2025). "The previous study showed that GISTs and renal cell carcinoma might occur as familial tumors related to a mutation in KIT." (PMID 32375797, 2020). "Pieces of evidence such as the drug combination of sunitinib targeted PDGFRA and sorafenib targeted KIT, was proved to be successful for renal cell carcinoma in clinical trial phase 3." (PMID 32523951, 2020). "Machine learning has demonstrated high accuracy in distinguishing CD117 (c-KIT) oncocytomas from the chromophobe subtype of renal cell carcinoma using the peak early enhancement rate (PEER), with a 95% accuracy for tumor type classification (100% sensitivity and 89% specificity)." (PMID 37686558, 2023). "Therefore, evaluating diagnostic usefulness as a biomarker, targeting the c-KIT and VEGFR pathways can possibly provide a potentially fit targeted tumor therapeutic modality against kidney cancer or renal cell carcinoma." (PMID 36354673, 2022). "For example, the immunotherapeutic drug pembrolizumab was used in combination with lenvatinib, a targeted drug that inhibits the activity of VEGFR, FGFR, PDGFRα, KIT and Ret, demonstrated promising anti-tumor effect in patients with renal cell carcinoma or endometrial cancer." (PMID 31673068, 2019). "Sorafenib, targeting VEGFR1-3, PDGFR-β, FLT-3, c-KIT, RAF kinases, for hepatocellular and renal cell carcinomas and thyroid cancer." (PMID 34956857, 2021). "Sunitinib, targeting VEGFR1-3, PDGFR-α/β, KIT, FLT-3, colony-stimulating factor receptor Type 1 (CSF-1R), RET, for gastrointestinal stromal and pancreatic cancers and renal cell carcinoma." (PMID 34956857, 2021).
hepatocellular carcinoma (35 papers, 2008 to 2025). A malignant tumor that arises from hepatocytes. "A previous study reported that higher level of soluble KIT in plasma was shown to be associated with enhanced survival in response to sorafenib (another TKI) treatment in advanced hepatocellular carcinoma." (PMID 32055239, 2020). "Lenvatinib primarily targets VEGFR and FGFR family members and, to a lesser extent, RET and KIT and is approved as monotherapy for the treatment of hepatocellular carcinoma and differentiated thyroid cancer." (PMID 36808802, 2023). "Moreover, these proteins might activate different signaling pathways leading to cancer progression, as seen for KIT in hepatocellular carcinoma." (PMID 33869179, 2021). "CD105, c-KIT, VEGFR1, and some other proteins are involved in maintaining the self-renewal and proliferation ability of CD90-positive hepatoma cells." (PMID 40253402, 2025). "External validation confirmed positive correlations for FAP and angiogenesis receptors FLT1, KDR, and KIT as well as HIF1A and ETS1 in hepatocellular carcinoma but also in metastatic prostate cancer (Dream Team cohort)." (PMID 36672341, 2023). "For instance, sorafenib, which can inhibit multiple tyrosine kinases including VEGFR1, VEGFR2, KIT, and PDGFR-α, is widely used in hepatocellular carcinoma (HCC) and renal cell cancer." (PMID 36568395, 2022). "Lenvatinib is a potential molecular target of KIT, PDGFR-α, and FGFR, and it shows antitumor activity in HCC (hepatocellular carcinoma) by targeting FGF/FGFR signaling; however, further investigation into its anti-FGFR activity is required." (PMID 34440080, 2021).
glioblastoma (34 papers, 2010 to 2025). The most malignant astrocytic tumor (WHO grade IV). "c-KIT, VEGFR2 and PDGFRα have previously been found to be amplified in 15–33% of primary glioblastomas and amplification of c-KIT and PDGFRα to be associated with poor survival of glioblastoma patients." (PMID 25025175, 2014). "Stem cell factor and KIT activation may play a role in the development and progression of glioma, and its mutation frequency is 4.4% in glioblastomas." (PMID 39767683, 2024). "PDGFRA and KIT too, may be expressed in the glioblastoma-associated vasculature, although they have been less extensively studied." (PMID 23990986, 2013). "The role of KIT expression in glioblastoma, and thus the necessity of targeting the receptor clinically, is less clear." (PMID 23990986, 2013). "Moderate or strong expression of KIT and phosphorylated (activated) KIT have been detected in tumor endothelial cells of glioblastomas, but only infrequently in a few other histological types of human cancer." (PMID 20030644, 2010). "Amplification of KIT in 17 (4.4%) glioblastomas was reveled from screening of 390 glioblastomas." (PMID 25079112, 2014). "There were few tumour phenotypic differences between receptor-positive and negative vessels, save for an increased proportion of oligodendroglial-predominant glioblastoma specimens with KIT positive endothelial cells (25/69, 36.2% vs 33/177, 18.6%, p = 0.0022, Fishers exact test)." (PMID 23990986, 2013). "In our hands, amplification of any of PDGFRA, KIT or VEGFR2 is found in nearly a quarter of glioblastoma cases, with individual genes ranging from 14–25%, which may itself be an underestimate due to sampling." (PMID 23990986, 2013). "In our sample, amplification or mutation of the EGFR gene, as well as amplification of the PDGFRA and KIT genes, potentially leading to their overexpression, were prevalent in HGG IDH—wildtype glioblastoma." (PMID 39684714, 2024). "In chromosomal region 4q12, PDGFRA, KIT, and KDR genes are localized, which play critical roles in development of glioblastoma." (PMID 39684714, 2024). "A novel multikinase inhibitor of MET, VERFR1, AXL, TIE2, KIT, FLT3, and RET, called cabozantinib (also known as XL184), inhibits the growth, metastasis, and angiogenesis in pancreatic cancer and glioblastoma, and reduces resistance to gemcitabine." (PMID 26225770, 2015). "Our smMIP technique detected amplification of PDGFRA, KIT and EGFR within tumor BI05, an IDH1-wild type glioblastoma." (PMID 25608559, 2014). "For example, single gene amplification of KIT on chromosome 4 can occur in testicular tumors, yet larger amplicons containing KIT, PDGFRA, and KDR are amplified in glioblastoma." (PMID 24874471, 2014). "A younger age at diagnosis and better clinical outcome in glioblastoma patients is only seen when PDGFRA and KIT are co-amplified." (PMID 23990986, 2013). "The alterations in FGFR4, KIT, and PEG3 were correlated with a short OS in astrocytoma, alterations in CDK4, FUBP1, and NTRK2 were correlated with a short OS in oligodendroglioma, and alterations in CDK4, CIC, FGFR3, and KMT5B were correlated with a short OS in glioblastoma." (PMID 36998447, 2023).
glioblastoma (continued). "In glioblastomas (GBM), the most common alterations were gene amplifications (PDGFRA, KIT, KDR, EGFR, and MET) and deletions (CDKN2A and PTEN)." (PMID 27172220, 2016). "KIT and phosphorylated KIT were present also in tumor endothelia of other types of pediatric brain tumors, such as ependymomas and medulloblastomas, suggesting that adult glioblastomas are not the only types of brain tumors that may express activated endothelial cell KIT receptor tyrosine kinase." (PMID 20030644, 2010).
mast cell leukemia (32 papers, 2006 to 2025). Mast cell leukemia is a malignant form of systemic mastocytosis (SM) characterized, most of the time, by the presence of circulating mast cells. "Here we report a 59-year-old male mast cell leukemia patient with KIT F522C mutation treated with midostaurin." (PMID 37638009, 2023). "CDK6 siRNAs were transfected in HMC1.1, a mast-cell leukemia carrying an endogenous point mutation in the juxtamembrane domain of KIT, and TF-1 cells stably transfected with the classical KIT D816V mutation." (PMID 27323399, 2016). "Vice versa, transfection of a KIT D816V mutation retained Ba/F3 cells highly resistant towards quizartinib, which is consistent with findings in the human mast cell leukemia cell line HMC1.2." (PMID 23497317, 2013). "Mast cell leukemia is a rare and aggressive disease, predominantly with KIT D816V mutation." (PMID 37638009, 2023). "HMC-1 cells containing common KIT variants, isolated from a patient with mast cell leukemia, remain one of the most frequent preclinical models to test the efficacy of drugs targeting oncogenic KIT activity and to predict signaling pathways and behavior of neoplastic mast cells." (PMID 37025992, 2023). "We found that (a) both groups frequently appear as mast cell leukemia (the most aggressive SM subgroup), (b) those patients cannot be assessed using conventional risk scores, (c) response to treatment is poor and (d) overall survival is worse than in KIT D816V-positive SM." (PMID 38339343, 2024). "We also followed the maturation of endogenous KIT in the mast cell leukemia HMC-1.1 cell line." (PMID 32161259, 2020). "To this end, we took advantage of the human mast cell leukemia cell line HMC-1 with KIT V560G mutation and TRKA expression, but no detectable NGF by flow cytometric analysis." (PMID 29088753, 2017). "In contrast to mast cell leukemia we found no clear-cut correlation between KIT mutation and MAGE gene expression: mutational analysis for KIT was found in 5/28 available samples and CT7 expression was detected in none and CT10 in 1 of 5 (20%) of these cases (primaries and metastasis)." (PMID 26161400, 2015). "GIST-T1 cells (KIT⊿560–578) grow in a manner dependent on KIT signaling on the Golgi, whereas HMC-1.2 (mast cell leukemia, KITV560G/D816V) requires pAKT on EL and pSTAT5 on the ER." (PMID 31484543, 2019). "This was carried out using mast cell leukemia cell line HMC-1.1, which relies on KIT signaling for survival and is highly sensitive to various KIT inhibitors, such as imatinib, dasatinib, and nilotinib." (PMID 30931942, 2019). "Consistent with KIT inhibition, nanomolar concentrations of GSK2606414 and KIRA6 were sufficient to induce cell death in a KIT signaling-dependent mast cell leukemia cell line." (PMID 30931942, 2019). "The mast cell leukemia cell line, HMC-1.1, was addicted to KIT that was blocked by dasatinib." (PMID 32161259, 2020).
glioma (31 papers, 2009 to 2025). A benign or malignant brain and spinal cord tumor that arises from glial cells (astrocytes, oligodendrocytes, ependymal cells). "Both PDGFRA and KIT are notable driver mutations of glioma, and were observed to be associated with poor prognosis in our cohort and TCGA glioma cohort." (PMID 36720864, 2023). "Concordantly, single amplification for KIT within the 4q12 amplicon was detected by CISH or FISH in 47% (15 out of 32) lower-grade gliomas harboring GA for only one of these 3 genes." (PMID 37610648, 2023). "In the H3 K27M‐mutant glioma, amplifications affecting the 4q12 region were also detected, in association with KDR‐PDGFRA, KIT‐PDGFRA, and KDR‐CHIC2 fusions, previously unreported in this entity." (PMID 35545820, 2022). "Detection of a BRAF V600E mutation next to mutations in NF1 and JAK3 as well as deletions of KIT and PDGFRA led to the diagnosis of a pediatric-type low-grade glioma or ganglioglioma." (PMID 32758285, 2020). "Amplifications and mutations of PDGFRA, KIT and KDR were found in 8-15% of RMPAhigh gliomas, followed by EPHB3 (7.7%), FGFR1 (5.9%), FGFR3 (5.9%) and MET (4.1%)." (PMID 27385209, 2016). "KIT expression is often observed in gliomas, and imatinib (which is known to inhibit c-Kit) is currently being evaluated in clinical trials." (PMID 20824129, 2010). "Furthermore, in human glioma cells EGFRvIII is distributed by extracellular vesicle-based transfer to activate other membrane-associated oncogenic tyrosine kinases such as HER2, KIT and MET57." (PMID 38123680, 2024). "Consistent with a potential role in angiogenesis, KIT is found on circulating endothelial precursor cells and human umbilical vein endothelial cells (HUVEC), and its ligand stem cell factor (SCF) has been implicated as both an autocrine and paracrine growth factor for gliomas." (PMID 23990986, 2013). "According to the Stupp protocol and metronomic dose of the temozolomide treatment, the mutated genes related to the second relapse of patients with high-grade glioma were PIK3C2B, KIT, ERBB3, and MLH1." (PMID 39767683, 2024). "The results showed that patients in different groups defined by age, FGFR2, IDH1, CDK4, CDK6, KIT, and CDKN2A had significantly different OS in all glioma grades." (PMID 37273702, 2023). "Age, FGFR2, IDH1, CDK4, CDK6, KIT, and CDKN2A were considered vital indicators related to the prognosis and OS time of glioma." (PMID 37273702, 2023). "Alterations in CDK4/6, CIC, FGFR2/3/4, FUBP1, KIT, MET, NF1, PEG3, RB1, and NTRK2 were additional factors correlated with the survival of different subtypes of gliomas." (PMID 36998447, 2023). "Based on their prognostic relevance in glioma samples, the seven variables age, FGFR2, IDH1, CDK4, CDK6, KIT, and CDKN2A were selected for the construction of the WHO5 risk signature." (PMID 37273702, 2023). "There were multiple, cancer type–specific hot spots of junctions located near known oncogenes such as KIT, PDGFRA, EGFR, CDK4, MDM2 (glioma), TMPRSS2, ERG (PCa), FGFR1, and CCDN1 (BrCa)." (PMID 34891161, 2021). "It turned out to be a selective FLT3, KIT, and PDGFR-β inhibitor and increased the apoptotic glioma-cell numbers and arrested sub-G1-phase cell cycle." (PMID 33218150, 2020). "Co-occurrence between amplification of EPHB3 and alterations in PIK3CA (both at chromosome 3q26-3q27), and amplifications in PDGFRA, KIT and KDR (all at 4q12) were also found in a subset of RMPAhigh gliomas, due to their localization in the common amplicons." (PMID 27385209, 2016). "In another study, Cediranib, a potent inhibitor of VEGFRs, which also targets KIT and PDGFRA, was shown to induce a significant reduction of U251 glioma cells in S phase and a higher percentage of apoptotic cells." (PMID 24922514, 2014). "The aim of this study was to assess the relative contributions of PDGFRA, KIT and VEGFR2 to high grade glioma tumour biology, in terms of gene amplification and expression in the tumour cells and associated vasculature." (PMID 23990986, 2013).